FRZB (frizzled related protein)
Description:
Soluble frizzled-related proteins (sFRPS) function as modulators of Wnt signaling through direct interaction with Wnts. They have a role in regulating cell growth and differentiation in specific cell types. SFRP3/FRZB appears to be involved in limb skeletogenesis. Antagonist of Wnt8 signaling. Regulates chondrocyte maturation and long bone development.
Synonyms: FRE; FRZB1; SFRP3; FRZB-PEN; SRFP3; FRP-3; FRITZ; FRZB-1; FZRB; hFIZ; OS1
Tractability: Antibody: UniProt places it where antibodies can reach, with high confidence; UniProt predicts a signal peptide or a membrane-spanning region; its Gene Ontology location is reachable by antibodies, with medium confidence.
Gene: Protein-coding gene on chromosome 2 (182,833,275 to 182,866,638, reverse strand). Ensembl gene ENSG00000162998.
Subcellular location: Secreted
Gene Ontology:
Molecular function: protein binding; Wnt-protein binding
Biological process: negative regulation of canonical Wnt signaling pathway; negative regulation of cell growth; negative regulation of cell population proliferation; negative regulation of Wnt signaling pathway; positive regulation of apoptotic process; positive regulation of fat cell differentiation; canonical Wnt signaling pathway; non-canonical Wnt signaling pathway; skeletal system development; neural crest cell differentiation; regulation of cell differentiation; somite development
Cellular component: extracellular region; cytoplasm; membrane
Genetic constraint (gnomAD): Loss-of-function variants: 25 observed, 22.98 expected, observed/expected ratio (o/e) 1.09, 90% interval 0.79 to 1.52. The upper end of that interval is the gene's LOEUF score, 1.52, which puts it in group 6 of 6, group 1 being the genes least tolerant of losing a copy. Missense variants: 366 observed, 364.93 expected, observed/expected ratio (o/e) 1, 90% interval 0.92 to 1.09. Synonymous variants: 157 observed, 144.76 expected, observed/expected ratio (o/e) 1.08, 90% interval 0.95 to 1.24.
Homologues: Orthologues: chimpanzee FRZB (100% identical), macaque FRZB (99% identical), pig FRZB (97% identical), rabbit FRZB (93% identical), dog FRZB (92% identical), guinea pig FRZB (92% identical), mouse Frzb (91% identical), rat Frzb (91% identical), tropical clawed frog frzb (74% identical), zebrafish frzb (65% identical), Drosophila melanogaster fz2 (28% identical), Caenorhabditis elegans cfz-2 (26% identical), and 4 more. Paralogues in human: SFRP4 (49% identical), FZD8 (30% identical), FZD7 (28% identical), FZD5 (28% identical), FZD1 (27% identical), FZD2 (27% identical), FZD10 (26% identical), FZD3 (25% identical), FZD9 (25% identical), FZD4 (25% identical), FZD6 (23% identical), SMO (20% identical), and 3 more.
Diseases named in the same sentence as FRZB in open-access papers:
FRZB is named in the same sentence as 124 diseases in open-access papers, as found by Europe PMC text mining. Sharing a sentence is not in itself a finding about the gene and the disease. The quoted sentences say what the papers report.
osteoarthritis (19 papers, 2010 to 2025). A noninflammatory degenerative joint disease occurring chiefly in older persons, characterized by degeneration of the articular cartilage, hypertrophy of bone at the margins and changes in the synovial membrane. "A novel lncRNA, AC005165.1, is dysregulated in osteoarthritis articular cartilage and subchondral bone, influencing the expression of the osteoarthritis risk gene FRZB, indicating potential therapeutic targets." (PMID 41158629, 2025). "Genes associated with DDH and osteoarthritis include FRZB, CX3CR1, ASPN, DKK1, PDRG1, GDF5, UQCC1, and TGF-β1." (PMID 41019141, 2025). "While FRZB, important in the progression of osteoarthritis, was decreased (FC = 0.26), mainly the inflammatory factors related to osteoarthritis such as IL1R (FC = 1.24), IL-1b (FC = 2.31), MMP9 and PTGS2 showed an increased expression after the intervention." (PMID 35159340, 2022). "FRZB acts as the WNT inhibitor, and loss of function of FRZB results from excessive WNT activation and increases susceptibility to osteoarthritis." (PMID 34360947, 2021). "In this study, we reported two SNPs of osteoarthritis-related genes, rs7775 in the FRZB gene and rs7033979 in the ASPN gene, showed significant associations with KBD in Tibetans." (PMID 28651521, 2017). "FRZB, a soluble antagonist of Wnt signaling, has been studied in osteoarthritis (OA) animal models and OA patients as a modulator of Wnt signaling." (PMID 24658359, 2014). "Nonetheless, clinical studies have shown that DKK1 and FRZB protein expression in serum and/or synovial fluid are expressed at significantly different levels in patients with osteoarthritis or rheumatoid arthritis compared with control." (PMID 24286177, 2013). "FRZB has been reported as a key factor of skeletal morphogenesis and osteoarthritis." (PMID 33245093, 2021). "Moreover, a genetic linkage has been shown between osteoarthritis and a SNP of the frizzled related protein (FRZB) gene, an antagonist of canonical Wnt signaling." (PMID 32079226, 2020). "In this study, we investigated whether factors implicated in osteoarthritis or regulation of chondrocyte hypertrophy influence GREM1, FRZB and DKK1 expression levels." (PMID 24286177, 2013). "Of note, FRZB and CHRDL2 were recently shown to have potential protective characteristics in osteoarthritis." (PMID 33382035, 2020). "Since in osteoarthritis development we found that FRZB was lost starting in grade 2, while DKK1 started to decrease in grade 1, we decided to test in our model if FRZB was able to prevent WNT activity when DKK1 expression was lost." (PMID 29165387, 2017). "Together, the current study demonstrates an inverse correlation between osteoarthritis and GREM1, FRZB and DKK1 gene expression in cartilage and provides insight into the underlying transcriptional regulation." (PMID 24286177, 2013). "The current study demonstrates that the mRNA expression of GREM1, FRZB and DKK1 is inversely correlated with the level of cartilage degeneration in osteoarthritis." (PMID 24286177, 2013). "We also earlier demonstrated that lack of extracellular Wnt antagonist frizzled-related protein increases the severity of osteoarthritis in mouse models." (PMID 28627522, 2017). "Based on these observations, we hypothesized that the expression of GREM1, FRZB and DKK1 is inversely correlated with osteoarthritis and their expression is influenced by established regulators of chondrocyte hypertrophy." (PMID 24286177, 2013). "Since osteoarthritis is associated with deregulated hypertrophic differentiation in at least a subset of patients, we hypothesized that GREM1, FRZB and DKK1 mRNA expression levels are downregulated in osteoarthritis." (PMID 24286177, 2013). "GREM1, FRZB and DKK1 mRNA expression were strongly decreased in osteoarthritis." (PMID 24286177, 2013).
osteoarthritis (continued). "Inhibitors of WNT (DKK3 and FRZB), and antagonists of BMP/TGFβ (CD109, CHRDL2, DCN FMOD, INHBA and THBS1) signalling were decreased or absent in the aged inner region, consistent with the reported upregulation of these pathways in IDD and its closely related condition osteoarthritis." (PMID 33382035, 2020). "WNT16 transient expression was found associated with the activation of the canonical WNT pathway, and was present in the early phases of osteoarthritis, its upregulation was accompanied by the downregulation of the secreted WNT inhibitor Frizzled-related protein (FRZB)." (PMID 26287176, 2015).
breast cancer (17 papers, 2008 to 2023). A primary or metastatic malignant neoplasm involving the breast. "SFRP1 encodes the secreted frizzled-related protein 1 which is a soluble Wnt antagonist, and its inactivation is known to be associated with unfavorable prognosis among breast cancer patients." (PMID 27786176, 2016). "For instance, NDST1, FRZB, ALAD, EDNRB, SSX2IP, and SFN have strong associations with breast cancer development, which bolsters our confidence in the viability of our model." (PMID 38007443, 2023). "The FRZB gene regulates Wnt signaling, and downregulation of the FRZB protein has been observed in breast cancer." (PMID 35625741, 2022). "Amongst the differentially expressed genes, we identified downregulation of secreted frizzled-related protein-1 (SFRP-1) in three Her2+ breast cancer cell lines." (PMID 25278993, 2014). "Increased expression of Wnt ligands was reported in breast cancer and dishevelled in cervical cancer, while decreased expression of dickkopf-1 was reported in pancreatic cancer, secreted frizzled-related protein 1 (SFRP1) in lung cancer, and WIF1 in cervical cancer." (PMID 27843945, 2016). "Mechanically, FMO2 was positively and highly correlated with secreted Frizzled-related protein 1 (SFRP1), which was downregulated in breast cancer due to hypermethylation." (PMID 37963835, 2023). "Moreover, it is suggested that the levels of endogenous negative regulators of Wnt/β-catenin including DKK1 and secreted frizzled-related protein-1 may be potentially employed as biomarkers for evaluating the beneficial effects of exercise on the metabolism and prognosis of breast cancer patients." (PMID 31511432, 2019). "Furthermore, a secreted frizzled-related protein 1 (SFRP1) is known to be responsible for hyperplasia, and thus, lack of SFRP1 is accompanied by both tumor development and poor prognosis for breast cancer." (PMID 33092068, 2020). "In addition, we excavated secreted Frizzled-related protein 1 (SFRP1), a known negative regulator of the Wnt/β-catenin pathway, from the perspective of co-expression analysis to reveal the potential molecular mechanism of FMO2 in breast cancer." (PMID 37963835, 2023).
heart failure (9 papers, 2015 to 2026). Inability of the heart to pump blood at an adequate rate to meet tissue metabolic requirements. "In animal models, secreted frizzled related protein 1 (Sfrp1) inhibition of the Wnt signaling pathway is beneficial because Sfrp1 reduces myocardial apoptosis and prevents heart failure." (PMID 27048460, 2016). "Its overexpression observed in our rTOF pigs is in accordance with these previous findings and confirm FRZB as a marker of cardiac failure due to overload." (PMID 26252659, 2015). "In particular, these data pointed out FRZB as a heart failure marker." (PMID 26252659, 2015). "The modules related to the Wnt receptor signaling pathway were limited to heart failure arising from HCM, with increased WIF1 and FRZB." (PMID 29160422, 2017). "Finally, five genes (FRZB, SFRP4, ETNPPL, AQP4, C1orf105) were found to be highly co-expressed in patients with heart failure and atrial fibrillation." (PMID 36295481, 2022). "Wnt signaling-related treatment may have potential benefits to patients with heart failure arising from HCM, and WIF1 and FRZB may be potential therapeutic targets." (PMID 29160422, 2017).
gastric cancer (7 papers, 2007 to 2025). A primary or metastatic malignant neoplasm involving the stomach. "It has been revealed that FRZB was upregulated in gastric cancer, and overexpression of FRZB impeded gastric cancer cell proliferation." (PMID 34364402, 2021). "This is the first study to elucidate the regulatory relationship between circCNIH4 and DKK2 or FRZB in gastric cancer; however, the precise molecular mechanism still needs to be further studied." (PMID 34364402, 2021). "We explored the role of secreted frizzled-related protein 1 (sFRP1) overexpression in gastric cancer and its relationship with radiological findings from dual-energy spectral CT(DEsCT) and positron emission tomography/computed tomography (PET/CT)." (PMID 28169332, 2017). "The methylation of the promoter region of the secreted frizzled-related protein 1 (SFRP1) holds potential as a diagnostic indicator and therapeutic target, particularly in specific malignancies like ampullary adenocarcinoma and gastric cancer, where its upregulation is linked to poor prognoses." (PMID 39236081, 2024). "CircCNIH4 induced the expression of DKK2 and FRZB in gastric cancer cells." (PMID 34364402, 2021). "In addition, a previous study displayed that knockdown of FRZB promoted cell growth through Wnt/β-catenin pathway in gastric cancer." (PMID 34364402, 2021). "Moreover, silencing of DKK2 or FRZB reversed circCNIH4 overexpression-mediated effects on gastric cancer cells." (PMID 34364402, 2021). "Similar to DKK2, FRZB also plays an inhibitory role in Wnt/β-catenin pathway in gastric cancer." (PMID 34364402, 2021). "Finally, the in vivo experiment indicated that circCNIH4 inhibited tumor growth via DKK2 and FRZB in gastric cancer." (PMID 34364402, 2021). "Also, knockdown of FRZB enhanced the activity of β-catenin and promoted cell growth in gastric cancer." (PMID 34364402, 2021). "Additionally, circCNIH4 suppressed tumor growth via regulating DKK2 and FRZB expression in gastric cancer in vivo." (PMID 34364402, 2021). "The role of secreted frizzled-related protein (SFRP) genes in gastric cancer remains largely unknown." (PMID 17848950, 2007). "Our study demonstrated that circCNIH4 played a tumor-inhibiting role through upregulating DKK2 and FRZB expression and suppressing Wnt/β-catenin pathway in gastric cancer, which might provide a potential biomarker for the diagnosis and treatment of gastric cancer." (PMID 34364402, 2021). "In our study, the restoration experiments demonstrated circCNIH4 suppressed gastric cancer cell progression via elevating the expression of DKK2 and FRZB to repress Wnt/β-catenin pathway." (PMID 34364402, 2021). "Then, we found Wnt antagonist genes DKK2 and FRZB were upregulated by circCNIH4 overexpression in MKN-74 and HGC-27 cells and proved that circCNIH4 played its function by regulating DKK2 and FRZB expression and inactivating Wnt/β-catenin pathway in gastric cancer cells." (PMID 34364402, 2021). "However, the regulatory mechanism between circHECTD1 and DKK2 or FRZB has not been elucidated in gastric cancer." (PMID 34364402, 2021).
lung carcinoma (7 papers, 2014 to 2022). "In a suggested mechanism, Rab37 mediates exocytosis of secreted frizzled related protein 1 (SFRP1), an antagonist of the WNT pathway, to suppress WNT signaling in lung cancer cells in vitro." (PMID 36317486, 2022). "Another study found that miR-1254 targeted secreted frizzled related protein 1 (SFRP1), a Wnt/β-catenin pathway antagonist, to promote lung cancer cell proliferation." (PMID 33403035, 2021).
pancreatic cancer (6 papers, 2013 to 2024). "Several studies have shown that FRZB is downregulated in pancreatic cancer, suggesting that this protein may play a role in pancreatic cell fate maintenance." (PMID 34566896, 2021). "FRZB expression was notably increased in Panc269, which has been found to progress pancreatic cancer through non-canonical Wnt signaling pathway." (PMID 38598488, 2024).
colorectal cancer (5 papers, 2009 to 2021). A primary or metastatic malignant neoplasm that affects the colon or rectum. "Epigenetic alterations have also been identified, including inactivation of secreted frizzled-related protein genes in colorectal cancer." (PMID 19293793, 2009).
breast tumors (4 papers, 2007 to 2023). "Moreover, many breast tumors show hypermethylation of the secreted Frizzled-related protein 1 (sFRP1) promoter region, causing low expression of this WNT antagonist." (PMID 19473496, 2009). "For example, expression of the extracellular inhibitor of WNT signaling, secreted Frizzled-related protein 1 (sFRP1), which competes with FZD receptors for ligand binding, is downregulated in many breast tumors and is associated with poor prognosis." (PMID 17897439, 2007). "Additionally, aberrant activation of the WNT signaling pathway has been detected in breast tumors, and the expression of Frizzled-related protein 1 (sFRP1), a secreted factor that inhibits WNT signaling, is downregulated in many breast tumors and associated with poor prognosis." (PMID 27487128, 2016). "Most breast tumors show hypermethylation of the promoter region of secreted Frizzled-related protein 1 (sFRP1), a negative WNT pathway regulator, leading to downregulation of its expression." (PMID 17897439, 2007). "Furthermore, most breast tumors show hypermethylation of the promoter region of secreted Frizzled-related protein 1 (sFRP1) and low expression of this negative WNT pathway regulator." (PMID 19473496, 2009).
glaucoma (4 papers, 2019 to 2021). Increased pressure in the eyeball due to obstruction of the outflow of aqueous humor. "Transforming growth factor-β2 (TGFβ2) and secreted frizzled-related protein-1 (SFRP1) levels were detected in aqueous humor levels (AH) samples from different glaucoma patients." (PMID 33578928, 2021). "Also, over-expression of secreted frizzled-related protein-1 (sFRP-1), a Wnt signaling antagonist, in glaucomatous TM cells has been demonstrated to be responsible for elevated IOP in glaucoma." (PMID 32641001, 2020).
hepatocellular carcinoma (4 papers, 2014 to 2024). A malignant tumor that arises from hepatocytes. "Secreted frizzled related proteins (SFRP1, SFRP2, SFRP3), which are Frizzled competitors for Wnt, are silenced by promoter hypermethylation in different cancers, including hepatocellular carcinoma (HCC), lung adenocarcinoma, oesophageal squamous cell carcinoma (ESCC) and CRC." (PMID 28931650, 2017).
melanoma (4 papers, 2011 to 2017). A malignant, usually aggressive tumor composed of atypical, neoplastic melanocytes. "The 12 CpG loci identified by PAM analysis that provided the most accurate prediction of melanoma were RUNX3_P393_R, RUNX3_P247_F, RUNX3_E27_R, COL1A2_E299_F, MPO_P883_R, TNFSF8_E258_R, CD2_P68_F, EVI2A_P94_R, OSM_P188_F, ITK_P114_F, FRZB_P406_F, and ITK_E166_R." (PMID 21375697, 2011). "This set of genes included forkhead box C1 (FOXC1), keratin 14 (KRT14), cyclin E1 (CCNE1), melanoma inhibitory activity (MIA) and secreted frizzled-related protein 1 (SFRP1), while expression of CDCA1 and MELK, (neither of which were detectable in MCF7), did not change following SOX11 depletion." (PMID 26894864, 2016).
renal carcinoma (4 papers, 2012 to 2022). A carcinoma arising from the epithelium of the renal parenchyma or the renal pelvis. "Since Wnt causes cancer cells to grow, it was originally hypothesized that sFRPs are inhibitors of cancer cell growth but a subsequent study revealed that sFRP-3 (also known as FrzB) is present at high levels in metastatic renal cancer tissues." (PMID 23408665, 2013). "In contrast, high expression of FRZB, MYBL2, MYL2, NETO2, PLSCR4, and TES predicts an unfavorable outcome in endometrial, head and neck, liver, pancreatic, and renal cancer." (PMID 36497479, 2022).
abdominal aortic aneurysm (3 papers, 2021 to 2023). Enlargement and ballooning of the vessel that supplies arterial blood to the abdomen, pelvis and legs. "It has been demonstrated that FRZB is a key molecule in the progression of abdominal aortic aneurysm, and it can reduce the growth and aggressiveness of fibrosarcoma cells." (PMID 36863704, 2023). "It has been reported that FRZB serves as a key molecule in abdominal aortic aneurysm progression and can decrease the growth and invasiveness of fibrosarcoma cells." (PMID 35850644, 2022).